TXN (thioredoxin)
Diseases named in the same sentence as TXN in open-access papers (continued):
Sharing a sentence is not in itself a finding about the gene and the disease.
cancer (continued). "Moreover, research indicates that targeting the thioredoxin system to induce tumor cell apoptosis might underlie the anti-cancer mechanisms of several therapeutic agents, including arsenic trioxide." (PMID 20707922, 2010). "In most cancer species, the TXN and TXNRD1 high expression groups and the TXNIP low expression group had lower stromal and immune scores." (PMID 39744566, 2025). "As established previously, cancer cells are addicted to their hyperactive antioxidant systems—the Nrf2, glutathione, and thioredoxin pathways—to survive high levels of endogenous ROS." (PMID 41154495, 2025). "Since many cancers overexpress the thioredoxin system, which confers drug resistance to cancer chemotherapy, there has been growing evidence in recent years that TrxR is a potential target for developing new anti-cancer drugs." (PMID 40599794, 2025). "Building on the thioredoxin network’s redox regulation of NF-κB, antioxidant enzymes like peroxiredoxins also modulate developmental pathways such as Hedgehog to sustain cancer stem cell properties and tumor progression." (PMID 41009046, 2025). "As an essential anti-oxidant system, thioredoxin system is required for either cancer cells or normal cells to survival." (PMID 40914135, 2025). "TXN is essential for the inflammatory response and is being investigated for its use in the treatment of many cancers." (PMID 40108736, 2025). "For instance, studies have found links to cancer, where elevated levels of thioredoxin have been observed." (PMID 38474110, 2024). "The concept of TXN inhibitors has emerged as an innovative domain within the realm of anti-cancer agents, imparting the capability to stimulate the generation of ROS." (PMID 39090114, 2024). "In cancer cells, in addition to ROS, antioxidant defense systems such as the thioredoxin (Trx) system increase their activity to cope with it." (PMID 38308689, 2024). "All these cancer cells release HMGB1 in the extracellular microenvironment together with varying concentrations of thioredoxin and thioredoxin reductase." (PMID 38803493, 2024). "The thioredoxin is an enzyme that catalyzes the reduction in disulfide bonds and it is overexpressed in cancer cells where it is detected both intracellularly and extracellularly." (PMID 39274973, 2024). "Intriguingly, a novel compound known as ferroptocide has emerged, functioning as a TXN inhibitor and thereby eliciting ferroptotic cell death in cancer cells." (PMID 39090114, 2024). "If both the GSH antioxidant pathway and the thioredoxin antioxidant pathway are blocked, the transformation of the cancer ceases." (PMID 38921002, 2024). "The upregulation of TXN and TXNRD in cancer cells enhances their proliferative and resistance to apoptosis, underscoring the TXN–TXNRD system as a promising target for therapeutic intervention." (PMID 39090114, 2024). "We found that HMGB1 is actively released by cancer cells together with the components of the thioredoxin system." (PMID 38803493, 2024). "Clinical studies on the inhibition of thioredoxin (Trx) for cancer therapy (for details, see the sections above)." (PMID 39334737, 2024). "The CXCL12/HMGB1 heterocomplex enhances, via CXCR4, the directional migration and invasiveness of cancer cells characterized by high metastatic potential that possess a fully active thioredoxin system, contributing to maintain red-HMGB1." (PMID 38803493, 2024). "In cancer cells, the activation of the thioredoxin system can promote tumor growth and survival, inhibiting apoptosis, thereby facilitating the development of cancer." (PMID 38685115, 2024).
cancer (continued). "The present work shed light on the activity of the CXCL12/HMGB1 heterocomplex on cancer cells, particularly those with a high metastatic potential and a functional thioredoxin system." (PMID 38803493, 2024). "The concentration-dependent ROS accumulation in PA-treated groups aligns with previous research suggesting the selective action of HDAC inhibitors against cancer cells through the thioredoxin–redox system." (PMID 38683491, 2024). "The glutathione-thioredoxin pathways are one of the most well researched endogenous antioxidant systems in cancer cells." (PMID 37627612, 2023). "The second issue is the concept of dual targeting of the glutathione and thioredoxin antioxidant systems because of their interconnection and compensatory nature, which has recently gained attention in cancer chemotherapy (and references therein)." (PMID 37569833, 2023). "Targeting the thioredoxin system thus seems to be another promising strategy to trigger ferroptosis and combat (therapy‐resistant) cancer." (PMID 36658724, 2023). "Tumor survival requires the inhibition of the death of intact cancer cells and promoting the death of damaged cancer cells, with TXN playing this role in cancer cell apoptosis, autophagy, and ferroptosis." (PMID 36776308, 2023). "Several studies have shown that cisplatin can reduce activity of thioredoxin reductase, leading to the lower level of TXN in resistant cancer cells." (PMID 37046833, 2023). "Dysfunction of the TXN system can lead to many health problems including metabolic syndrome, cancer, cardiovascular disease, and neurodegeneration." (PMID 37303736, 2023). "TXN is highly expressed in various cancers and regulates cell proliferation and apoptosis through different signaling pathways." (PMID 36776308, 2023). "For that reason, the conjugates reported in this study were meticulously designed to ensure the selective release of their cytotoxic agent only upon binding to GnRHR I to cancer cells via the thioredoxin system." (PMID 37894912, 2023). "Mechanistic studies revealed their ability to accumulate into cancer cells and to selectively target Thioredoxin (TrxR), thus leading to redox homeostasis unbalance and ultimately inducing cancer cell death through apoptosis." (PMID 36835512, 2023). "NADPH can support the biosynthesis of GSH, thioredoxin, and CoQ10 to boost the antioxidant defense in cancer cells and protect cancer cells from ferroptosis and cell death." (PMID 37842240, 2023). "The glutathione-thioredoxin pathway plays an important role in protecting cancer cells from excessive ROS levels generated during cell metabolism." (PMID 37627612, 2023). "Cancer cells are heavily dependent on antioxidant molecules, including those of the thioredoxin system, to maintain this balance and counteract increased ROS production, which is usually detected in cancer cells due to their abnormal metabolic activity." (PMID 36830087, 2023). "Obviously, the expression of TXN in the tumor group was higher than that in the control group, implicating TXN as a cancer promoting factor." (PMID 36776308, 2023). "Thioredoxin-1 (TXN), a redox balance factor, plays an essential role in oxidative stress and has been shown to act as a potential contributor to various cancers." (PMID 36776308, 2023). "Studies found that TXN is overexpressed in most cancers, which can be responsible for drug resistance in tumorigenesis." (PMID 37684566, 2023). "The thioredoxin-thioredoxin reductase (Trx/TrxR) system plays a key role in cancer and is a novel drug target for regulating cancer cell stress." (PMID 36313365, 2022). "Recently, the TXN system was reported to be related to the immunogenic cell death of cancer cells, suggesting promising roles of TXN and TXNRD1 for immune modulation." (PMID 36615301, 2022). "PX-12, the first TXN inhibitor to undergo clinical development, is a potential therapeutic agent for cancer treatment." (PMID 35597868, 2022).
cancer (continued). "Au inhibits the thioredoxin antioxidant system, thus increasing the overall peroxide burden on cancer cells." (PMID 35624835, 2022). "Due to the elevated intracellular ROS present in cancer cells, the expression of the thioredoxin antioxidant system has been shown to be upregulated in many tumor types." (PMID 35326683, 2022). "The thioredoxin (Trx) system, a key antioxidant pathway, represents an attractive target for cancer therapy." (PMID 35344158, 2022). "A recent study has demonstrated that targeted inhibition of glutathione and thioredoxin antioxidant pathways can synergistically kill cancer cells, suggesting that antioxidant systems are important for the initiation and progression of cancer cells." (PMID 34290233, 2021). "Many types of cancer have been shown to be dependent on redox-regulating mechanisms, such as the glutaredoxin and thioredoxin systems, and are therefore vulnerable to changes and offer a promising anticancer target." (PMID 34456713, 2021). "Moreover, a recent study reported genetic knockdown of TXN leads to accumulation of lipid ROS levels and induces an antioxidant response to cause ferroptosis, a potential pro‐ferroptotic agent due to its inhibition of TXN would be an anti‐cancer therapeutic strategy." (PMID 33528895, 2021). "The thioredoxin and thioredoxin receptor has been reported to be overexpressed in many cancer cells, as it allows for cancer cells to defend themselves against oxidative stress, thus decreasing in apoptosis." (PMID 32679649, 2020). "It binds to TrxR and irreversibly inhibits the enzymatic activity of both purified and cellular TrxR, resulting in marked elevation of oxidized thioredoxin and ROS in cancer cells." (PMID 32029902, 2020). "Both effects were reversed by NAC, suggesting that endogenous oxidative pressure in cancer cells was responsible for these oxidative DNA lesions following inhibition of the thioredoxin antioxidant system by ATL." (PMID 32029902, 2020). "The thioredoxin (Trx) system has been verified to participate in the regulation of redox balance in cancer cells, which contains Trx, Trx reductase (TrxR), and Trx-interacting proteins." (PMID 32596335, 2020). "Further analysis revealed that these compounds target to redox systems such as GSH and thioredoxin and induce accumulation of reactive oxygen species in nutrient-deprived cancer cells, potentially contributing to apoptosis under nutrient-deprived conditions." (PMID 32978257, 2020). "In some studies, a paradoxical role has been discussed for thioredoxin; it prevents cancer; on the other hand, it acts in its development." (PMID 33289312, 2020). "As ATL is known to inhibit thioredoxin reductase (TrxR), our results suggested that the thioredoxin antioxidant system likely plays critical roles in most cancer cells." (PMID 32029902, 2020). "Another antioxidant is the thioredoxin/thioredoxin reductase (Trx/TrxR) system, which is shown to be upregulated in cancer cells and is correlated with cancer aggressiveness and drug resistance." (PMID 33260826, 2020). "Following cancer onset, glutathione’s antioxidant function can become superfluous in some cancer subtypes due to thioredoxin antioxidant pathway fulfilling the antioxidant requirements making inhibition of only GSH insufficient for tumor therapy." (PMID 33050144, 2020). "Recently, auranofin and other inhibitors of the thioredoxin system have been proposed as novel anti-cancer therapies." (PMID 29194002, 2019). "As example, the small molecule drug BSO has been used in several clinical trials to combat different forms of cancer and has recently been re-vitalized due to highly promising results when co-targeting thioredoxin systems in cancer and HIV treatment." (PMID 31254735, 2019). "The inhibition of the TXN system leads to cancer cell death; however, the mechanisms and signaling pathways mediating the death are complex." (PMID 30861284, 2019).
cancer (continued). "Supportively, antioxidants such as glutathione and thioredoxin were often related to resistance against chemotherapy in various cancers." (PMID 31629402, 2019). "Thioredoxin (Trx) and thioredoxin reductase (TrxR) are the main components of the thioredoxin system, which is overexpressed in many cancer types, among them, CRC." (PMID 31195711, 2019). "Thioredoxin (Trx) and thioredoxin reductase (TrxR), known as antioxidant agents and anti-apoptotic proteins, commonly are overexpressed in the human cancer cells." (PMID 31652732, 2019). "Because GSH and thioredoxin pathways synergistically contribute to cancer cell survival, it has been suggested that blocking both GSH and thioredoxin pathways inhibits cancer promotion." (PMID 29971019, 2018). "Several proteins - such as Ras, Jun N-terminal kinase (JNK)- 2, AP-1, NF-kappaB, PKC, caspase, thioredoxin and p5349,50 - which are known to have important roles in cancer, are regulated by thiol oxidation." (PMID 29934500, 2018). "Although Tg(TXN)+/0 mice showed accelerated cancer development, the later part of lifespan was similar to WT mice, i.e., lifespan was not shortened by enhanced tumor development." (PMID 30370017, 2018). "Hyper-activation of Thioredoxin (Trx1) and thioredoxin reductase (TrxR1) has been reported in numerous cancer cells to regulate their ROS homeostasis, promotes cell growth and induce apoptotic resistance." (PMID 29391428, 2018). "The presence of increased ROS levels is a known feature of tumor microenvironment and induction of the thioredoxin/thioredoxin reductase (TXN/TXNRD1) system is known to be beneficial for the survival of cancer cells." (PMID 29755668, 2018). "Consistent with the overlapping function of the GSH and TXN system, the inhibition of TXNRD rendered cancer cells susceptible to the depletion of GSH." (PMID 30198844, 2018). "The inhibition of thioredoxin (Trx) results in the suppression of cancer cell invasion and metastasis." (PMID 29891764, 2018). "Results showed that the expression of TXN was detected in a number of human cancer tissues, including liver, colon, pancreas and uterine cervix indicating the possible involvement of TXN in the process of oncogenesis." (PMID 28107202, 2017). "The thioredoxin is a small protein playing pivotal roles in redox homeostasis and cell survival, and it is usually highly expressed in many cancers." (PMID 28686225, 2017). "NADPH, sourced from G6PD fuels nucleotide biosynthesis, maintains redox potential of thioredoxin and glutathione and drives the mevalonate pathway that powers many of the basic mechanisms by which cancer cells escape host control." (PMID 29955429, 2017). "Several cancers display increased expression of TXN and thioredoxin reductase 1 (TXNRD1) to compensate for GSH deficiency in GCLM−/− cells." (PMID 28744456, 2017). "The compensatory function of thioredoxin also provides an explanation for the resistance of epidermal keratinocytes to various anti-cancer drugs, of which many affect GSH metabolism." (PMID 26808544, 2016). "There are various ways as to how the thioredoxin system contributes toward the progression of cancer (Arnér and Holmgren, 2006)." (PMID 27065873, 2016). "TrxR is a critical component of the mammalian thioredoxin system and is overexpressed in many cancer cells." (PMID 27164131, 2016). "Nevertheless, TXNRD/TXN is known to play important roles in cancer progression and anticancer therapy." (PMID 26657290, 2016). "Recent interest in the thioredoxin system as a therapeutic target for cancer has heightened interest in gold compounds, including AF." (PMID 26573231, 2016).
cancer (continued). "Thioredoxin reductase biochemically reduces thioredoxin which mediates the final step of the electron-transfer pathway for nucleoside diphosphate reduction where in cancer cells is essential for cell growth and survival." (PMID 25821636, 2015). "An increase in thioredoxin levels seen in many human primary cancers compared to normal tissue appears to contribute to increased cancer cell growth and resistance to chemotherapy." (PMID 25871387, 2015). "Nuclear translocation of TXN activates transcriptional factors involved in cellular redox regulation and impacts high infiltration and/or metastatic capability of cancer cells." (PMID 26325518, 2015). "Because of its role in stimulating cancer cell growth and as an inhibitor of apoptosis, thioredoxin offers a target for the development of drugs to treat and prevent cancer." (PMID 25871387, 2015). "This review focuses on the cross-talk between thioredoxin and DJ-1 and highlights the importance and consequences of targeting thioredoxin and DJ-1 together to develop an effective anti-cancer therapeutic strategy." (PMID 25593990, 2014). "This review focuses on two antioxidant systems, Thioredoxin and DJ-1, which are upregulated in many human cancer types, correlating with tumour proliferation, survival, and chemo-resistance." (PMID 25593990, 2014). "The thioredoxin system has emerged as a potential therapeutic target for the treatment of many human cancer types using compounds that specifically target the thioredoxin system to induce cancer cell apoptosis." (PMID 25593990, 2014). "Amongst all the members of thioredoxin system, Trx1 and TrxR1 have emerged as critical redox regulators and as potential therapeutic targets for many human cancer types." (PMID 25593990, 2014). "Involvement of glutathione S-transferase and thioredoxin has long attracted the attention of cancer researchers." (PMID 25221514, 2014). "TXN has also been evaluated as a biomarker and therapeutic target for cancer, and it is known that TXN levels can be used to indicate potential chemotherapy resistance." (PMID 23389041, 2013). "Collectively, these analyses suggest that elevated glutathione synthesis and thioredoxin pathway activity are common features of cancer cells." (PMID 24342878, 2013). "Thioredoxin is known to have important roles in both these cellular responses and several studies implicate thioredoxin as a contributor to cancer progression." (PMID 24281068, 2010). "In summary, we show that parthenolide modulates cancer cell exofacial thiols, including that of surface thioredoxin." (PMID 19956548, 2009). "It is becoming increasingly evident that the thioredoxin system is of major importance for cancer development and as a target for anticancer therapy." (PMID 18382651, 2008). "Moreover, a newly developed silver molecule cluster, Ag5, demonstrated strong anti‐tumor activity by concurrently inhibiting glutathione and thioredoxin signaling pathways, diminishing its anti‐oxidant effect in cancer cells." (PMID 40377005, 2025). "Literature also suggests that inhibiting the pathway mediated by TXN may aid in the treatment of inflammatory diseases and cancer." (PMID 40124361, 2025). "Another antioxidant defense system for cancer cells is the thioredoxin (Trx) system." (PMID 38785550, 2024). "Thioredoxin reductase plays a regulatory role in its metabolic activity by catalyzing the reduction of thioredoxin and may play an important role in the prevention and treatment of cancer." (PMID 39846017, 2024). "The imbalance in TXNIP/TXN expression and stromal inflammation leading to increased level of ROS may explain the frequent development of precursor lesions and cancer in ESRD/ACRD kidney." (PMID 39020292, 2024). "In cancer cells, increased TXN expression increases proliferation and cell survival." (PMID 39175079, 2024).